MRPL17 (mitochondrial ribosomal protein L17)
Synonyms: L17mt; MRP-L17; LIP2; RPML26; MRP-L26; bL17m; RPL17L
Tractability: Small molecule: a structure with a bound ligand is known. PROTAC: ubiquitination databases record sites on it; its protein half-life has been measured.
Gene: Protein-coding gene on chromosome 11 (6,680,385 to 6,683,401, reverse strand). Ensembl gene ENSG00000158042.
Subcellular location: Mitochondrion
Pathways (Reactome):
Metabolism of proteins: Mitochondrial ribosome-associated quality control; Mitochondrial translation elongation; Mitochondrial translation initiation; Mitochondrial translation termination
Gene Ontology:
Molecular function: protein binding; protein domain specific binding; structural constituent of ribosome
Biological process: mitochondrial translation; translation
Cellular component: mitochondrial large ribosomal subunit; mitochondrion; mitochondrial inner membrane; ribosome
Genetic constraint (gnomAD): Loss-of-function variants: 10 observed, 14.04 expected, observed/expected ratio (o/e) 0.71, 90% interval 0.44 to 1.21. The upper end of that interval is the gene's LOEUF score, 1.21, which puts it in group 5 of 6, group 1 being the genes least tolerant of losing a copy. Missense variants: 263 observed, 251.08 expected, observed/expected ratio (o/e) 1.05, 90% interval 0.95 to 1.16. Synonymous variants: 107 observed, 98.78 expected, observed/expected ratio (o/e) 1.08, 90% interval 0.93 to 1.27.
Homologues: Orthologues: chimpanzee MRPL17 (99% identical), macaque MRPL17 (98% identical), rabbit MRPL17 (91% identical), pig MRPL17 (89% identical), rat Mrpl17 (86% identical), guinea pig MRPL17 (85% identical), mouse Mrpl17 (85% identical), tropical clawed frog mrpl17 (63% identical), zebrafish mrpl17 (63% identical), Caenorhabditis elegans mrpl-17 (31% identical).
Diseases named in the same sentence as MRPL17 in open-access papers:
MRPL17 is named in the same sentence as 13 diseases in open-access papers, as found by Europe PMC text mining. Sharing a sentence is not in itself a finding about the gene and the disease. The quoted sentences say what the papers report.
lung carcinoma (4 papers, 2022 to 2024). "Another study targeted gene associated with lung cancer and found four key genes that may affect lung cancer prognosis: MTIF2, ACOX1, CAV1, and MRPL17." (PMID 35039759, 2022).
lung adenocarcinoma (2 papers, 2021 to 2025). A carcinoma that arises from the lung and is characterized by the presence of malignant glandular epithelial cells. "Transcriptomic analyses of TCGA and single-cell RNA sequencing data revealed significant upregulation of MRPL17 in LUAD (lung adenocarcinoma) and LUSC (lung squamous cell carcinoma) tumor tissues, particularly within malignant epithelial and proliferating cancer cells." (PMID 41422086, 2025). "Upregulation of MRPL22 (HR = 1.5, p = 0.0048), MRPL28 (HR = 1.5, p = 0.0098), MRPL21 (HR = 1.7, p = 0.001), MRPL12 (HR = 1.7, p = 0.00059), MRPS12 (HR = 1.6, p = 0.002), and MRPL17 (HR = 1.5, p = 0.0051) were correlated with poor overall survival in lung adenocarcinoma." (PMID 34925439, 2021). "The Cytoscape with cytoHubba tool kits, GEPIA, and c-BioPortal analysis suggested that upregulated hub genes of MRPL22, MRPL28, MRPL21, MRPL12, MRPS12, and MRPL17 are correlated with poor overall survival and may play a key role by cooperating with ALDOA in lung adenocarcinoma." (PMID 34925439, 2021).
breast carcinoma (1 paper, 2020). "Five additional loci were newly associated with both DA and breast cancer risk in the same direction, identifying LMNB1, MKX, PRKG1, MRPL17, and SMIM25 as candidate genes for both DA and breast cancer risk." (PMID 33037222, 2020).
endometrial cancer (1 paper, 2024). Primary or metastatic malignant neoplasm involving the endometrium (mucous membrane that lines the endometrial cavity). "highlighted MRPL17 as a crucial pathogenic factor in endometrial cancer." (PMID 39742265, 2024).
liver cancer (1 paper, 2024). An epithelial or non-epithelial malignant neoplasm that arises from the liver. "This study experimentally validated MRPL17 as a promising prognostic biomarker, emphasizing the need to target liver cancer stem cells to improve patient prognosis and enhance treatment effectiveness." (PMID 39742265, 2024).
tumor (2 papers, 2024 to 2025). "Numerous prior studies have recognized MRPL17 as a significant marker for tumor prognosis." (PMID 39742265, 2024). "Finally, through the ssGSEA algorithm, we assessed enrichment scores for multiple pathways to explore the association of MRPL17 expression with these pathways, revealing a positive relationship between MRPL17 expression and tumor proliferation as well as EMT." (PMID 39742265, 2024). "By integrating the expression levels of these genes across various pathological stages and conducting correlation analyses with tumor stemness, we discovered that MRPL17 serves as an important stem cell marker gene pertinent to the prognosis and progression of LIHC." (PMID 39742265, 2024).
MRPL17 also shares sentences with these, for which no sentence is quoted: cancer (1 paper); epilepsy (1); glioma (1); leukemia (1); lipoid proteinosis (1); lung squamous cell carcinoma (1); non-small cell lung carcinoma (1).